GAL (galanin and GMAP prepropeptide)
Diseases named in the same sentence as GAL in open-access papers (continued):
Sharing a sentence is not in itself a finding about the gene and the disease.
cancer (26 papers, 2011 to 2025). A tumor composed of atypical neoplastic, often pleomorphic cells that invade other tissues. "GAL-CGem consists of a galactose-substituted coumarin scaffold linked to gemcitabine, an anti-cancer drug." (PMID 38543094, 2024). "This study establishes GAL-CGem as a promising theranostic system that is selectively activated in cancer cells with high levels of β-galactosidase while sparing neighboring healthy cells from adverse effects." (PMID 38543094, 2024). "Among the most recurring ligands, we found several instances that are either invariably associated to lower survival, e.g., CXCL5, CXCL1, GAL, and RPS19, or have opposite associations depending on the cancer type, e.g., CXCL9." (PMID 38723607, 2024). "Prostaglandin E2 promotes cancer invasion by promoting the secretion of pro-inflammatory mediators and neuropeptides by tumor cells, GAL released by cancer induces neuritogenesis, facilitating PNI." (PMID 36900158, 2023). "Considering the diverse role of the GAL system in cancer, and its mitogenic effect on cholangiocytes, it is conceivable that the GAL system is involved in the carcinogenesis of CCA." (PMID 37443714, 2023). "In human stomach samples, obtained from the vicinity of invasive cancer cells, neurons located in the myenteric plexus showed a high expression of both caspases 3 and 8, but a low expression of GAL." (PMID 35954419, 2022). "TWIST1 and ADAM22 were also positively correlated with cancer stage, while GAL was an independent OS predictor in addition to MYCN and age." (PMID 32629858, 2020). "The synergistic relationship between tunicamycin and GAL-012 revealed above is not only novel, but also offers support to our proposed targeting of glycosylation in cancer cells." (PMID 32028604, 2020). "For example, in cultures of small-cell lung cancer cell lines, GAL was found to act as a cancer growth factor by stimulation of the MAPK mitogenic pathway." (PMID 32403316, 2020). "Recent studies have demonstrated that the relative frequency of GAL-IR neurons inside MP increase in the human colon and stomach wall affected by cancer." (PMID 30373200, 2018). "Prostaglandin E2 promotes cancer invasion, and in a feedback mechanism, GAL released by cancer induces neuritogenesis, facilitating perineural invasion." (PMID 29758011, 2018). "There is no detailed data describing the distribution pattern of CART+/GAL+ neurons in the MP in the stomach wall affected by cancer." (PMID 30373200, 2018). "It has only been reported that, in patients with CRC, GAL concentrations were higher within the muscular layer of the colon wall located in the vicinity of cancer invasion, compared to the sections distally from it." (PMID 30373200, 2018). "This is the first report on the co-localization pattern of CART and GAL in the neural structures of the human stomach, especially in regions affected by cancer infiltration." (PMID 30373200, 2018). "Genes that have been previously associated with MD and various other cancers showed differential marks that are either MD-induced (MX1, CTLA-4, EAF2 and GAL) or line-specific (IGF2BP1 and MMP2)." (PMID 23072359, 2012). "The GAL system that has known anti-proliferative effects in other cancers is also revealed to be potentially involved in MD progression." (PMID 23072359, 2012). "In contrast, the correlation between high expression of GALR1 in the submucosal plexuses and overall survival of CRC patients suggest that GAL and GALRs can act as a components of local neuro-paracrine pro-proliferative pathways accelerating the invasion and metastasis of cancer cell." (PMID 36551197, 2022). "The galaninergic system is expressed in normal tissues and, in cancer cells, is involved in tumorigenesis, invasion and migration (metastasis), although in some tumors, GAL and GALRs are silenced." (PMID 35954419, 2022).
cancer (continued). "Neuropeptides such as galanin (GAL), angiotensin II, apelin, adrenomedullin, endothelin-1, bombesin, orexin, substance P, neuropeptide Y, calcitonin gene-related peptide, vasoactive intestinal peptide and neurotensin are involved in cancer." (PMID 35954419, 2022). "In addition, a relationship between a high GAL expression and the spread of cancer stem cells (metastasis) has also been reported in CRC (stage II)." (PMID 35954419, 2022). "Following a similar feedback manner, GAL secreted by cancer cells induces neurogenesis and PNI." (PMID 33946706, 2021). "In this way, GAL could not only be a neuroprotective factor, but it also can play an important role in cancer progression." (PMID 32403316, 2020). "Such gene and protein up-regulation within CRC tissue may suggest that GAL is produced and secreted by cancer cells and acts as a mitogen within cancer tissue in an autocrine way." (PMID 32403316, 2020). "To assess whether the two other UDP-hexose pyrophosphorylases which GAL-012 recognizes can potentially offer additional advantages in controlling cancer cell growth, we must validate the other two targets." (PMID 32028604, 2020). "GAL may play a dual role in cancer regulation because it exhibits different expression profiles in cancers." (PMID 32724813, 2020). "The present results also indicated that the percentage of GAL-IR neurons (within the CASP3-IR population of neurons) in the MPs located close to the cancer-affected stomach wall was significantly lower compared to macroscopically-unchanged part of the stomach wall." (PMID 30019295, 2018). "However, further studies are necessary to elucidate, in detail, the exact role of CART and GAL in cancer-affected human stomach." (PMID 30373200, 2018). "Additionally, in the LML and LMM, the density of CART+/GAL+ nerve fibers was significantly lower in the surgical margin, compared to cancer-affected region (respectively)." (PMID 30373200, 2018). "Therefore, the GAL system is considered to be a promising candidate for detection and treatment of various cancers." (PMID 23072359, 2012). "In addition, neurogenic galanin (GAL) activates the G protein-coupled receptor galanin receptor 2 (GALR2) in tumors to induce NFATC2-mediated transcription of cyclooxygenase-2 and GAL, which causes the crosstalk between nerves and cancer cells." (PMID 36900158, 2023). "Thus, due to the crucial role that GAL plays in cancer, the aim of this review is to show the involvement of the galaninergic system in this disease and to suggest potential therapeutic strategies to block the development of tumors using GAL receptor antagonists or agonists." (PMID 35954419, 2022). "In carcinoma-affected regions of the human stomach, an increase of the GAL-immunoreactive fibers in the longitudinal muscle layer, lamina muscularis mucosae and in the vicinity of the neoplastic proliferation was observed; thus, carcinoma invasion affected GAL stomach wall innervation." (PMID 35954419, 2022). "Interestingly, in the preset work, the percentage of CART+ and/or GAL+ neurons was similar in both studied samples, whereas the number of nerve fibers containing these peptides significantly increased in the muscle layers of the cancer-affected region." (PMID 30373200, 2018). "Our studies have shown that, in the cancer-affected wall, there were visible increases in the number of CART+/GAL+ nerve fibers in the LML and LMM, as well as GAL-IR in the CML and LMM." (PMID 30373200, 2018). "Notable changes in the dense network of CART+/GAL+ nerve fibers (an increase) were observed in the LML and lamina muscularis mucosae (LMM) within carcinoma-affected areas of the human stomach." (PMID 30373200, 2018). "In this study, the researchers focused on creating a multicomponent “glycoprotein” by incorporating a fluorescent glycoprobe galactosyl dicyanomethylene-4H-pyran (GAL-DCM) and an anti-cancer drug (Maytansine) into the hydrophobic pockets of HSA." (PMID 38543094, 2024).
cancer (continued). "There is no detailed data describing the distribution pattern of GAL-IR neurons in the MPs of cancer-affected stomach wall." (PMID 30019295, 2018). "Moreover, triple-immunofluorescence staining revealed that the number of GAL+ nerve fibers in the CML and LMM distal from cancer invasion was lower than cancer-affected region." (PMID 30373200, 2018). "In the case of GAL, there is no detailed data describing the distribution pattern of these nerve fibers in the cancer-affected stomach wall." (PMID 30373200, 2018). "Importantly, GAL’s antiproliferative potency was much higher in GAL2R-expressing cells than in those expressing GAL1R, meaning that a high level of GAL2R could block cancer cell proliferation." (PMID 35954419, 2022). "Furthermore, the present results indicated that the high percentage of neurons containing GAL and low percentage of CASP-8 in the MPs of cancer-affected stomach wall might also reflects neuroprotective role of this peptide." (PMID 30019295, 2018). "In our preliminary experiment, immunohistochemical analysis showed GAL was expressed in all CRCs examined and localized predominantly to the cytoplasm of the carcinoma cells, whereas none of the non-cancerous colonic mucosa demonstrated positive immunostaining of GAL (data not shown)." (PMID 25504183, 2015). "Moreover, our results showed that cancer did not change the frequency of neurons containing CART with GAL, or devoid of CART but positive for GAL." (PMID 30373200, 2018).
neurodegenerative disease (8 papers, 2017 to 2024). A disorder of the central nervous system characterized by gradual and progressive loss of neural tissue and neurologic function. "GAL also has neurotrophic properties and has been directly implicated in neurodegenerative diseases." (PMID 30717384, 2019). "It is generally known and accepted that GAL shows neuroprotective functions during brain injury and neurodegenerative diseases." (PMID 35804576, 2022). "In turn, GAL plays neuroprotective roles in the brain and peripheral nervous system, especially during traumatic brain injury, cerebral focal and neurodegenerative diseases." (PMID 29558425, 2018).
infection (5 papers, 2012 to 2025). The state of being infected such as from the introduction of a foreign agent such as serum, vaccine, antigenic substance or organism. "We observed an increase in H3K27me3 levels on GAL after infection in both lines." (PMID 23072359, 2012). "BuChE performance was observed when AChE was suppressed, with increased activity in the GAL/INF group similar to the INF group on the 30th day post infection, thus corroborating the absence of a significant difference in parasitic curves and histopathological analysis." (PMID 34787259, 2021).
adenocarcinoma (2 papers, 2022 to 2024). A common cancer characterized by the presence of malignant glandular cells. "Studies showing the colocalization of CART- and/or GAL-positive neurons in a stomach with adenocarcinoma have demonstrated that the number of these fibers increased in the neoplastic area compared with the area showing no abnormal cells." (PMID 39519197, 2024). "GAL mRNA is overexpressed in CRC and its level has been related to adenocarcinoma size/stage and a correlation between shorter disease-free survival of early-stage CRC patients and high expression of GAL has been reported." (PMID 35954419, 2022).
gastrointestinal disease (2 papers, 2020 to 2022). A disease that occurs in the gastrointestinal system, excluding the hepatobiliary system. "Due to the large number of described physiological functions of GAL in the gastrointestinal tract, there is a growing interest in the role of GAL in the development of gastrointestinal diseases." (PMID 33552060, 2020).
CNS tumors (1 paper, 2020). "Despite its strong expression in the central nervous system (CNS), the role of GAL in CNS tumors has not been extensively studied." (PMID 32265844, 2020).
mitochondrial disease (1 paper, 2025). "Eight patients had IBGC (variants in SLC20A2, PDGFB, MYORG), 4 had mitochondrial disease (MT-TL1), and 2 had monogenic vascular conditions (GAL, MAP3K6)." (PMID 40947452, 2025).
GAL also shares sentences with these, for which no sentence is quoted: acute liver failure (15 papers); Hepatitis (11); injury (10); liver failure (9); liver disease (7); Acute hepatitis (5); Fulminant hepatitis (5); Sepsis (4); inflammation (3); liver cancer (3); liver fibrosis (3); memory impairment (3); Opioid Dependence (3); Fulminant hepatic failure (2); kidney disease (2); steatosis (2); acromegaly (1); acute endometritis (1); Acute hepatic failure (1); alcohol use disorder (1); alcoholic liver diseases (1); alcoholism (1); autoimmune disease (1); bacterial infections (1); bladder cancer (1); bowel dysfunction (1); breast tumors (1); cardiac arrhythmia (1); cardiac hypertrophy (1); cardiomyopathy (1).
A further 41 diseases each share a sentence with GAL in 1 paper.